TGFB1 (transforming growth factor beta 1)
Diseases named in the same sentence as TGFB1 in open-access papers (continued):
Sharing a sentence is not in itself a finding about the gene and the disease.
infection (continued). "Expression levels lower than the constitutive gene were found for the PDGF, EGF, TGFβ1, and FGF before infection, and these basal levels were used for the calculation of ΔΔCT." (PMID 30333964, 2018). "In this work, we analyzed the production of the growth factors EGF, TGFβ1, PDGF, and FGF during the infection by Leishmania parasites, the development of the injuries and the early response to treatment." (PMID 30333964, 2018). "Lastly, pattern "Yers-Salm" includes 1,694 genes whose expression levels changed preferentially after infection with Y. pseudotuberculosis or S. typhimurium (e.g. TLR8, TGFB1, IL18)." (PMID 26586179, 2015). "Currently, we demonstrated that TGFβ1 and SAG maintain BBB integrity and suppress BMECs immune reaction induced by meningitic E. coli, which indicated protective potential of HH signaling agonist onto CNS upon infection." (PMID 38360663, 2024). "In contrast to IRF3-driven expression, transcription of the NF-κB-dependent genes Nfkbia and Tgfb1 was not affected by the presence or absence of M35 during infection." (PMID 37289084, 2023). "TGFb1-positive ILCs were detected 3 days after infection and were more abundant in the absence of IL-10." (PMID 36016413, 2022). "HRV16 infection also led to a significant increase in expression of genes involved in EMT (e.g., COL1A1, MMP9, SNAI1, and ZEB2) and growth factors (e.g., ~ fourfold for EGF and FGF2, and to a lesser extent TGFB1)." (PMID 34140575, 2021). "Additionally, the expression of transforming growth factor beta 1 (TGF-β1) and mannose-binding lectin 2 (MBL2) have been identified as gene modifiers for CF and infection severity." (PMID 32630625, 2020). "Accordingly, production of TGF-β increased in BMDMs upon infection without changes in Tgfb1 mRNA abundance." (PMID 32479529, 2020). "Directly after infection, naïve CD4+ T cells activate and differentiate into different subsets of functional T cells, such as IFN-γ-secreting T-helper type 1 (Th1) cells, transforming growth factor-beta 1- (TGF-β1-) secreting T regulatory cells (Tregs), and interleukin- (IL-) 4-secreting Th2 cells." (PMID 31686983, 2019). "One month after infection, EGF and TGFβ1 were expressed in all hamsters with inverse ratio." (PMID 30333964, 2018). "While the EGF and FGF levels decreased between day 15 and 30 of infection, the TGFβ1 increased and the PGDF levels did not change." (PMID 30333964, 2018). "Infection by L. (V) braziliensis induced the expression of all the growth factors in ID15, with levels of induction with respect to healthy hamsters of: PDGF 0.4 ± 0.1, EGF 3.9 ± 0.2, FGF 1.1 ± 0.5, and TGFβ1 0.4 ± 0.2." (PMID 30333964, 2018). "We did not record any modulation of the TGFB1 mRNA levels during our short term infection in this study." (PMID 28684793, 2017). "So, TGFβ-1 gene infected hMSC can still further promote cell proliferation than hMSC without gene infection." (PMID 26003220, 2015). "We observed a significant 2.5-fold increase in the IL10 transcript in sorted splenic CD4 T cells at day 250 after infection (P<0.05), with no changes in the expression of TGFB1." (PMID 24763747, 2014). "In mice, transcript levels of Tgfb1 after MHV68 infection or bleomycin treatment showed comparable levels between Cyb5r3fl/fl and Cyb5r3 SPC–KO mice; however, relative expression of TGF-β1 target genes after injury was significantly different in the fl/fl or SPC-KO mice." (PMID 36749633, 2023). "Despite the short treatment duration and no evident changes in weight loss or Tgfb1 expression, the CYB5R3-deficient mice on the sGC activator diet after MHV68 infection showed less collagen deposition and decreased expression of pro-fibrotic and pro-senescent markers." (PMID 36749633, 2023).
infection (continued). "Pro-inflammatory (IFNγ, IL-6, TNFα), Treg (IL-10, TGFβ1, TGFβ3), Th9 (IL-9), Th17 (IL-17), and Th2 (IL-4, IL-13) cytokines, total IgM and IgG, as well as gene expressions of FoxP3, STAT5+, IFNγ-R1, and ROR alpha+, were measured at day 1, day 7, day 14, day 21, and day 28 post-infection." (PMID 37569646, 2023). "Finally, overnight infection did not trigger significant changes in production of TGFβ-1, IL-8, IFN-γ, and IL-6 by the co-culture." (PMID 28345602, 2017). "In the present study, TGFB1 mRNA was not increased by the infection with Ad-TGFBR2." (PMID 23457527, 2013). "Immunofluorescence microscopy revealed TGFβ1 production throughout the nephron but primarily in the thick ascending loop and distal tubule in both vehicle and TC‐treated mice, both before and 1 day post infection, with no significant TGFβ1 production in the medulla." (PMID 32227630, 2020). "Moreover, administration of a TGFβ receptor antagonist did not alter global TGFβ1 production in the kidney early in infection, but did result in reduction of the activated myofibroblast population in the injured, androgenized (and therefore scar‐susceptible) host." (PMID 32227630, 2020). "Infection with A7UF induced an increased expression of Ccl2, Icam1, Tgfb1, Eng, and matrix metalloproteinase (Mmp) 2 and 9 with no change in the expression of the tissue inhibitor of metalloproteinase (Timp)." (PMID 36483452, 2022). "An infiltration of CD4+CD25+T cells into the BF, and elevated expression of bursal TGFβ-1+ mRNA was observed at all time points following infection, irrespective of the strain or age of the birds, but CD4+TGFβ+cells and CD4+CD25+TGFβ+ cells only appeared in the BF at 28 dpi in younger birds." (PMID 37744374, 2023). "Beside these common markers, some genes were modulated in animals acutely infected by specific strains: Tnf was downregulated by X10 infection, Nos2 for X10 and VFRA, Arg1 for Esm and 10R, while infection with CM17 and Sc43 strains did not lead to modulation of Tgfb1 gene expression." (PMID 28827716, 2017).
kidney disease (372 papers, 2007 to 2026). "Inflammatory markers such as Transforming Growth Factor Beta 1, High Motility Group Box 1 and Urinary Monocyte Chemoattractant Protein- 1 are also increased in AS and indicate a higher risk of kidney disease progression." (PMID 35806283, 2022). "It has been shown that single nucleotide polymorphism (SNP) at codon 10 (Pro10Leu) and codon 263 (Thr263Ile) of Tgfb1 is associated with the development of nephropathy in type 1 diabetes." (PMID 34360646, 2021). "The HCC TME, in which we report frequent upregulation of CAF-SULF2, is characterized by activation of the TGFβ1 signalling pathway known to induce SULF2 in renal disease." (PMID 36589727, 2022). "We previously showed that urinary TGFβ1 contributed to the prediction of kidney disease progression in a cohort of patients with established DKD." (PMID 34572299, 2021). "Transgenic mice over-expressing TGFβ1 develop progressive renal failure, suggesting that chronically elevated levels of circulating TGFβ1 are integral to the pathogenesis of kidney disease." (PMID 17319955, 2007). "Similarly, a study by Schrameck and colleagues explored the expression of NRPs in fibrotic kidney disease and showed that TGFβ1 downregulates the expression of NRP1 in fibrotic renal tissues." (PMID 38646784, 2024). ",A number of anti-fibrotic agents, including Norcantharidin, Cordyceps sinensis, IL-7, proteasome inhibitor(MG132 and lactacystin), mycophe and PXS25 have been shown to inhibit the TGFβ1-induced Smad2 pathway in both animal models of renal disease and in cultured tubular cells." (PMID 25658916, 2015). "Furthermore, cumulating studies support the profibrotic effects of TGFβ1 in human kidney diseases." (PMID 35765067, 2022). "The fibronectin-assembling integrin α5β1 was shown to be upregulated by TGFβ1 in MCs and by HG in both MCs and podocytes, but has not as yet been directly shown to promote kidney disease." (PMID 36140347, 2022). "We therefore stimulated TECs with factors thought important for pEMT and kidney disease: angiotensin II (AngII), basic fibroblast growth factor (bFGF), endothelin 1 (ET-1), reactive oxygen species (H2O2), platelet-derived growth factor (PDGF), or TGFβ1." (PMID 36470928, 2022). "Other studies targeting TGFβ1 and αSMA in kidney diseases are in accordance with our results; however, no studies have used exosomes for the treatment of fibrosis associated with CKD during the menopause period." (PMID 35625591, 2022). "Elevated in both human and experimental kidney diseases, MCP1 secretion is triggered by interleukin-1, tumour necrosis factor-alpha and interferon-gamma, all of which were induced in our model by TGFβ1, yet blocked when co-applied with danegaptide." (PMID 33802083, 2021). "Elegant studies from the Fernandes laboratory have related the delayed onset and decreased severity of renal disease exhibited in fish oil-fed NZBWF1 mice to reduced IL-1β, TNF-α, TGFβ1, ICAM-1 and fibronectin expression and increased expression of antioxidant enzymes." (PMID 27513935, 2016).
cardiovascular diseases (159 papers, 2006 to 2025). "Various TGFβ1 polymorphisms were so far investigated to ascertain their possible involvement in the occurrence of several cardiovascular diseases, and they were selected on the basis of their peculiar localization." (PMID 18312614, 2008). "However, the interaction analysis reveals that such fluxes can significantly amplify the effect size of risk variants mapped to the PLG, BCAR1 and TGFB1 risk loci, respectively, providing insights into their roles in cardiovascular disease." (PMID 40175777, 2025). "A number of studieshave shown that the G allele of the rs1800471 polymorphism is associated with ahigher level of gene expression and elevated blood level of TGFβ1.Dysregulation of the TGFβ1 signaling pathway caused by a mutation can beassociated with an increased risk of cardiovascular diseases." (PMID 35127145, 2021). "For example, topological module 6 has six genes, of which EGLN, TGFB1, TGFR1, and TGFR2 are disease genes associated with Bone and Cardiovascular diseases, which we therefore label as a disease module." (PMID 26399914, 2015). "Studies investigating the relationship between transforming growth factor beta-1 proprotein (TGFB1) and cardiovascular diseases are relatively limited." (PMID 40649979, 2025). "Recently, the compound Si-Miao-Yong-An decoction (SMYAD), an inhibitor of the TGFβ1/Smad and TGFβ1/TAK1/p38 signaling pathways, was administered to TAC mice to assess its effects on cardiovascular disease development." (PMID 39451203, 2024). "There is first evidence that PLK2 regulates fibrosis formation in cardiovascular disease and differential regulation of PLK2 gene expression was found in Transforming Growth Factor beta 1 (TGF-β) treated adult lung fibroblasts." (PMID 33799608, 2021). "Transforming growth factor beta 1 (TGF-β1) is a polypeptide member of the transforming growth factor beta superfamily of cytokines and actively involved in many pathological processes of cardiovascular diseases." (PMID 32477156, 2020). "Luteolin plays positive role against cardiovascular disorders by improving cardiac function, decreasing the release of inflammatory cytokines and cardiac enzymes, prevention of cardiac fibrosis and hypertrophy; enhances level of CTGF, TGFβ1, ANP, Nox2, Nox4 gene expressions." (PMID 39830909, 2025).
inflammation (137 papers, 2006 to 2026). Aberrant reaction of the microcirculation characterized by movement of fluid and leukocytes from the blood into extravascular tissues. "However, in chronic airway inflammation due to repeated antigenic stimulation, persistently high levels of TGFβ1 can cause tissue fibrosis and airway remodeling, exacerbating the anti-inflammatory response induced by TGFβ1." (PMID 29854030, 2018). "Conditional deletion of Tgfb1 in T cells results in systemic autoimmune inflammation, demonstrating the fact that TGF-β1 produced by T cells helps maintain immune homeostasis." (PMID 30071700, 2018). "PSCs can be activated by pancreatic chronic inflammation, with cytokines and growth factors (e.g., IL-1β, IL-6, tumor necrosis factor alpha, or TNF-α, transforming growth factor beta 1, or TGF-β1) acting as stimulating molecules." (PMID 37296886, 2023). "In DSS-induced intestinal inflammation, mucosal Il6 and plasmatic SAA correlated positively with BLI, while Tgfb1 correlated negatively in the therapeutic approach." (PMID 37047397, 2023).
kidney (88 papers, 2005 to 2026). "On the other hand, in an older Chinese population, the TGFB1 polymorphism (rs4803455) was found to be significantly associated with an increased number of common carotid artery (CCA) plaques, as well as a larger carotid plaque area." (PMID 41150748, 2025). "Specifically, TGFβ1 signaling dysregulation plays a pivotal role in colorectal carcinogenesis by governing cell growth, differentiation, migration, and apoptosis." (PMID 40145096, 2025). "Transforming growth factor beta 1 (TGF-β1) is an inhibitor of muscle cell differentiation that is associated with fibrosis, poor regeneration and poor function in some diseases of muscle." (PMID 21152098, 2010). "In the presence of kidney injury, elevated beta-catenin levels lead to fibrosis due to the increased activation of various beta-catenin dependent pathways involved in the fibrotic response, such as the Wnt signaling pathway, the renin-angiotensin system, and Tgfb1/Smad pathway." (PMID 32555682, 2020). "Upon analysis, expression of the cytokines IFNB1, IFNG (IFN-γ), TNF (TNF-α), TGFB1 (TGF-β), IL1B, IL2, IL6, CXCL8 (IL-8), and IL10 were all significantly increased in ‘mesenchymal’ lung ADC compared to ‘epithelial’ tumors." (PMID 29440769, 2018). "This study demonstrated CEACAM6, LGR5 and Wnt pathway suppression by CD151 silencing might occur through TGFβ1 regulation, offering a comprehensive view of CD151's roles in colorectal carcinogenesis." (PMID 33767593, 2021).
heart disease (81 papers, 2008 to 2026). "Some studies have suggested that polymorphism in the TGFB1 gene is associated with heart disease in the general population." (PMID 22513132, 2012). "As proinflammatory/profibrotic mediators are also augmented in cardiac disease, the effect of a range of proteins, including Ang II, TGFβ1, IL-1β, IL-1α, TNFα, IL-6 and IL-6 in combination with the sIL-6R on Cx43 mRNA expression was examined in CFs." (PMID 31909243, 2020). "Among these genes are TGFβ1, IL10, and MYD88 which are known to participate in cardiac disease." (PMID 36248879, 2022).
adenocarcinoma (68 papers, 2007 to 2025). A common cancer characterized by the presence of malignant glandular cells. "Despite the lack of a statistically significant association between the transcript level of the TGFB1 gene and the degree of histological malignancy, a tendency was noticed to achieve higher relative expression levels of this gene by G1 and G2 adenocarcinomas as compared to G3." (PMID 35798776, 2022). "TGFβ1 and TGFβ2 have been implicated in FOXP3 induction in peripheral Tregs and adenocarcinoma expansion." (PMID 36973425, 2023). "βigh3 (keratoepithelin), also known as TGFβ1, is a transforming growth factor-β (TGF-β)-induced extracellular matrix (ECM) protein that was first identified in human adenocarcinoma cells." (PMID 17982418, 2007). "In the transgenic adenocarcinoma of mouse prostate (TRAMP) model, activated effector CD4+ T cells have been reported to release active TGFβ1." (PMID 30832732, 2019). "The TGFβ1 serum levels decreased at stages II and III adenocarcinomas, although only at stage III adenocarcinoma a significant difference was achieved versus controls." (PMID 22848630, 2012). "For example, in adenocarcinoma cell lines, CK2 activity is necessary for TGFβ-1-induced invasion." (PMID 28134850, 2017). "As regards TGFβ1 serum levels, a negative trend was observed at stages II and III adenocarcinomas, with a significant difference only at stage III." (PMID 22848630, 2012).
vasculopathy (66 papers, 2007 to 2025). "Blocking MPA formation or reducing platelet TGFβ1 may provide potential biomarkers and therapeutic targets for KD vasculopathy." (PMID 39665236, 2025). "Notably, mice deficient in platelet TGFβ1 show less MPA and CD14+CD16+ monocytes, along with reduced inflammation and vasculopathy." (PMID 39665236, 2025). "Thus, targeting MPA or reducing platelet TGFβ1 might provide novel therapeutic approaches for KD vasculopathy." (PMID 39665236, 2025). "Platelet (Plt)–TGFβ1 knock out (KO) (TGFβ1fl/flPF4‐Cre) mice were generated and administered with LCWE to determine whether platelet TGFβ was required for MPA‐mediated vasculopathy in vivo." (PMID 39665236, 2025).
neurodegenerative disease (65 papers, 2007 to 2026). A disorder of the central nervous system characterized by gradual and progressive loss of neural tissue and neurologic function. "Activation and priming of microglia have been demonstrated to contribute to the progression of neurodegenerative diseases and, thus, underlie stringent control by endogenous regulatory factors including TGFβ1." (PMID 30275444, 2018). "The contradictory findings, revealing both protective and damaging TGFβ1 roles, suggest its functions in neurodegenerative disease pathogenesis are highly context‐dependent." (PMID 38970443, 2024). "Neurodegenerative diseases suppress TGFβ1 leading to perturbed microglial homeostasis, supporting that decreased TGFβ1 can indicate declining brain health and activated microglial states." (PMID 33917279, 2021). "The study highlights the vital role of transforming growth factor beta-1 (TGF-β1) in managing neuroinflammatory responses and supporting the recovery of neural functions, offering valuable insights into potential therapeutic approaches for neurodegenerative diseases." (PMID 40299512, 2025). "It has also been proposed that excessive oxidative processes may be a mechanism of activation of latent TGFB pool in ALS, as in other neurodegenerative diseases, leading to an increased TGFB1 release from the complex." (PMID 32560258, 2020).
metabolic disorders (56 papers, 2010 to 2026). "The relationship between different genetic variants and BMI in KOA patients has been shown, among which there are a large number of genes associated with metabolic disorders (FTO, ADIPOQ, LEP, SREBP2) and other genes (GDF5, TGFB1, etc.)." (PMID 38424630, 2024). "Importantly, recent RNA sequencing data of KS transcriptomes compared to KS lesions show KSHV-mediated global transcriptional reprogramming that, similarly to our MSC tumors, included upregulation of the transforming growth factor-beta 1 (TGFB1) signaling pathway and glucose metabolism disorders." (PMID 31881074, 2019).
bacterial infection (49 papers, 2005 to 2025). "In CF, TGFB1 is activated by bacterial infection, malabsorption or nutritional status and also by polymorphisms in the TGFB1 gene itself." (PMID 41158431, 2025). "Variable selection using FS-PLS identified 4 genes distinguishing MIS-C from KD, viral and bacterial infections: HSPB1 Associated Protein 1 (HSPBAP1), Vacuolar Protein Sorting-Associated Protein 37C (VPS37C), Transforming Growth Factor Beta 1 (TGFB1) and MX Dynamin Like GTPase 2 (MX2)." (PMID 37255317, 2023). "One study investigated the interplay between TGFβ1 and MBL2 in a cohort of 1019 Canadian paediatric CF patients, reporting that high TGFβ1 production enhanced the modulatory effect of MBL2 on the age of first bacterial infection and the rate of decline of lung function." (PMID 33924524, 2021).
immune disorders (49 papers, 2007 to 2026). "Altogether, TGFβ1 is clearly involved in immune dysfunction following alcohol use, but more information is necessary to conclude that changes in TGFβ1 contribute to alterations in RHAMM signaling." (PMID 35634317, 2022).